TLR3 (toll like receptor 3)
Diseases named in the same sentence as TLR3 in open-access papers (continued):
Sharing a sentence is not in itself a finding about the gene and the disease.
Subdural Effusion (1 paper, 2017). Leakage and accumulation of CEREBROSPINAL FLUID in the subdural space which may be associated with an infectious process; CRANIOCEREBRAL TRAUMA; BRAIN NEOPLASMS; INTRACRANIAL HYPOTENSION; and other conditions. "For TLR3 rs3775291, the minor allele T carriers (CT+TT) were associated with a decreased incidence of subdural effusion (OR = 0.578, 95%CI: 0.337–0.992, P = 0.046) and seizures (OR = 0.500, 95%CI: 0.279–0." (PMID 28202935, 2017).
T-cell lymphoma (1 paper, 2017). "This is the first report about the function of TLR3 in chicken T-cell lymphoma, especially in signal pathway." (PMID 28790362, 2017).
temporal lobe epilepsy (1 paper, 2023). A localization-related (focal) form of epilepsy characterized by recurrent seizures that arise from foci within the temporal lobe, most commonly from its mesial aspect. "Previously, TLR3 deficiency in a pilocarpine model of temporal lobe epilepsy (TLE) was shown to reduce mortality, spontaneous recurrent seizures (SRS) and neuroinflammation." (PMID 37694107, 2023).
tetanus (1 paper, 2024). A serious infectious disorder that follows wound contamination by the Gram-positive bacterium Clostridium tetani. "Mitogen/antigen induced lymphocyte proliferation panel, lymphocyte enumeration panel, tetanus and pneumonoccocal antibody titers, and whole exome sequencing of TLR3 gene were completed for further workup." (PMID 39045035, 2024).
trichomoniasis (1 paper, 2022). An infection that is caused by Trichomonas. "TVV has also been reported to induce mammalian host Toll-like receptor 3 (TLR3) proinflammatory signaling, causing exacerbation of trichomoniasis lesions—associated to preterm birth and HIV susceptibility." (PMID 36327251, 2022).
upper respiratory tract infection (1 paper, 2021). "A phase 2 trial was conducted for common cold using oral homeopathic antibody as a tablet formulation against the TLR3 FYW peptide (TAO1); it showed efficacy against moderate-to-severe upper respiratory tract infection (NCT01651715)." (PMID 33805888, 2021).
urothelial carcinoma (1 paper, 2025). A malignant neoplasm derived from the transitional epithelium of the urinary tract (urinary bladder, ureter, urethra, or renal pelvis). "Additionally, we predicted the treatment response of TLR3 expression to immune checkpoint blockade using the anti-PD-L1 cohort of urothelial carcinoma (IMvigor210)." (PMID 40406122, 2025).
vaginal infection (1 paper, 2023). "Toll-like receptor 3 (TLR3) and toll-like receptor 9 (TLR9)-mediated antiviral defense were not expressed during vaginal infection with herpes simplex virus 2 in IFN-λR1 knockout mouse." (PMID 36911685, 2023).
viral pneumonia (1 paper, 2018). Inflammation of the lung parenchyma that is caused by a viral infection. "In the present study, we find that OMT can significantly decrease the expressions of TLR3, TLR4, TLR7, MyD88, and TRAF6 genes after IAV infection, and we preliminarily speculate that OMT may inhibit IAV proliferation and IAV viral pneumonia via inhibiting TLRs signaling pathways." (PMID 29570670, 2018).
infection (618 papers, 2007 to 2026). The state of being infected such as from the introduction of a foreign agent such as serum, vaccine, antigenic substance or organism. "Conversely, the detrimental effect of the TLR3 pathway on viral susceptibility and pathogenesis is closely related to the upregulation of immunogenic markers during infections." (PMID 39988665, 2025). "This reduction infection was associated with decreased mRNA expression of TLR3 and TLR7, along with increased expression of antiviral genes, including PKR and OAS1." (PMID 40839599, 2025). "In HTLV-1 infection, a single study examined polymorphisms in the TLR3 gene, identifying TLR3 rs3775296 as a potential protective factor against infection." (PMID 40831704, 2025). "The protective effect of TLR3 activation during infection has been shown in multiple viral groups with TLR3-deficient mice." (PMID 39988665, 2025). "Surprisingly, a higher viral load in TLR3-deficient mice paradoxically showed a reduced lung pathology and a high survival rate of the mice compared to wild-type mice upon i.n. infection with 300 pfu of IAV." (PMID 38892096, 2024). "On the other hand, TLR9 induces cytokine production and activation of Th1 responses, and a triple defect in TLR3, 7, and 9 made mice more susceptible to the infection." (PMID 39000601, 2024). "Using a model of multicellular spheroids, it was demonstrated that infection with the SARS-CoV-2 virus causes activation of RNA-recognizing receptors TLR3 and TLR7/8." (PMID 39457048, 2024). "The immune response TLR3 induces appears to provide a protective role for neurons and peripheral tissues during infection, but causes damage and increased permeability at the BBB." (PMID 36851477, 2023). "The results of the meta-analysis suggest a significant association between the TLR3 rs3775291 polymorphism and susceptibility to infections." (PMID 37510216, 2023). "A meta-analysis of 18 studies consisting of 3118 cases and 4368 controls found a significant association for risk between the presence of the TLR3 SNP rs3775291 and infections as part of the general analysis (OR = 1.16, 95% CI = 1.04–1.28, p = 0.004)." (PMID 37510216, 2023). "It is urgent to carry out more large-sample and high-quality studies in Asian regions, in order to continue investigating the link between the TLR3 rs3775290 gene polymorphism and infections by HCV." (PMID 37869679, 2023). "The meta-analysis carried out in this study explored the correlation between the rs3775291 polymorphism of the TLR3 gene and the risk of infection and disease development in different countries." (PMID 37510216, 2023). "As a consequence, the association between this TLR3 gene polymorphism and the infection by HCV cannot yet be considered statistically significant." (PMID 37869679, 2023). "Homozygous carriers of the minor allele of TLR3 (rs3775291) had higher infection-free survival compared with reference allele carriers (60.0% for TT versus 42.3% for CC/CT genotypes; P-value = 0.050)." (PMID 35967300, 2022). "Mice deficient in TLR3 show increased viral burden and impaired pulmonary function upon infection with mouse-adapted SARS-CoV (MA15)." (PMID 36419185, 2022). "TLR3 mediates important innate immune signaling that produces pro-inflammatory and anti-viral cytokines against infection, thus, loss of YAP/TAZ enhances host innate immune response and protects mice from lung injuries induced by IAV infection." (PMID 35503798, 2022). "Adult mice deficient in TLR3 were previously shown to be more susceptible to RV with a higher RV burden at the peak of infection." (PMID 35464475, 2022). "Enhanced neuroinvasiveness and increased infection susceptibility were also detected in an intravaginal HSV-2 infection model of TLR3‒/‒ mice, further highlighting the importance of TLR3 and its downstream signaling in host protection against HSE." (PMID 34696494, 2021).
infection (continued). "HSV-1(Herpes Simplex Virus type 1) infection: monitoring of the cell response were developed and tested by using cells harboring mutations in the TLR3 pathway." (PMID 33505391, 2020). "Some of these genes are controlled by Dnase2, Ikbkg, Il17a, Snca, Stat2, Tlr3 and their induction is associated with suppression of infection." (PMID 32793510, 2020). "Patients carrying a TLR3 +95C/A exhibit a phenotype of loss of function of DCs, which is correlated with a severe infection by A. fumigatus and deficiency in the activation of CD8 T cells." (PMID 33194839, 2020). "Our data showed that there were significantly higher amounts of C. muridarum in the UGTs of TLR3-deficient mice within the first seven days of infection when compared to wild-type controls." (PMID 30625140, 2019). "Claudin-1 protein expression levels seemed to slightly diminish at late times post-infection in the TLR3-deficient OE cells, and its cellular distribution remained mostly cytoplasmic throughout infection." (PMID 30625140, 2019). "Because of this altered immune response to C. muridarum infection, we routinely observe higher bacterial burdens early and mid-infection, and more substantial reproductive tract pathology in the TLR3-deficient mice." (PMID 30625140, 2019). "qPCR, immunoblotting, transwell permeability assays, and TER studies show that Chlamydia compromises cellular TJ function throughout infection in murine OE cells and that TLR3 deficiency significantly exacerbates this effect." (PMID 30625140, 2019). "Having shown the involvement of TLR3 in detecting EV-A71 infection, we next aimed to understand the underlying mechanism of this detection." (PMID 30563052, 2018). "There were 14.1% and 18.7% CD8+ T-cells in the wild-type and TLR3-deficient mice, respectively, at day 7 post-infection, which indicated a 9.8% and 16.01% increase over mock controls." (PMID 29624589, 2018). "In a separate report, however, TLR3-deficient mice had higher viral loads in the liver and heart and were more susceptible to infection." (PMID 30369921, 2018). "TLR3 deficient mice (TLR3−/−) are reported to be resistant to infection with the WNV and the influenza virus." (PMID 30374352, 2018). "Further, their work demonstrated that TLR3-deficient mice were more vulnerable to EV-A71 infection than wild-type mice." (PMID 30563052, 2018). "NOD mice deficient for TLR3 have high mortality from CVB4 infections and the few that survive develop T1D." (PMID 29018409, 2017). "In the TLR3/TLR4-associated subnetwork from the chronic stage of infection, JUN has the highest node degree and betweenness values." (PMID 28487699, 2017). "The susceptibility of TLR3 KO mice was so extreme that only 35% of mice survived more than 13 days of infection with a 100-fold lower viral load." (PMID 28973047, 2017). "In this study, Module 3 extracted from the TLR3/TLR4-associated subnetwork at the acute stage of infection contains five nodes that play crucial roles in My88-independent TRIF-dependent TLR signaling." (PMID 28487699, 2017). "For instance, infection caused by L. guyanensis paradoxically induces a specific immune response via TLR3 early after infection that impairs killing of parasites." (PMID 26904694, 2016). "Studies have shown that TLR3 plays a fundamental role in the expression of proinflammatory cytokines such as IL-6 and IL-1beta in fibroblasts or classical dendritic cells derived from TLR3-deficient mice after infection with NDV." (PMID 26975566, 2016). "Although both MQ-NCSU and HD11 are macrophage cell lines, it has been shown that their TLR3 expression, functions, responsiveness, and susceptibility to infection are different." (PMID 25165812, 2014). "Infection of mice deficient in TLR3 (TLR3−/−) with Friend retrovirus (FV) complex revealed higher viral loads during acute retroviral infection compared to wild type mice." (PMID 25539593, 2014).
infection (continued). "These TLR3-mediated immune responses render mice more susceptible to infection, and the animals develop an increased footpad swelling and parasitemia." (PMID 24762979, 2014). "In fact, TNF-α and IL-6 have been shown to contribute to the leakiness of the BBB caused by the TLR-3 mediated infection of mice with WNV." (PMID 24236107, 2013). "RV1B-infected, OVA-sensitized and -challenged mice with TLR3 deficiency demonstrated significantly lower airways responsiveness to inhaled methacholine one day after infection than similarly-infected and -treated wild-type mice." (PMID 21637773, 2011). "In general, TLR3-deficient mice with allergic airways disease showed similarly attenuated inflammatory responses to RV1B infection, leading to reduced airways responsiveness." (PMID 21637773, 2011). "BBB breakdown in the context of WNV is dependent on the Toll-like receptor (TLR)-3, since TLR-3 deficient mice exhibit increased survival when compared with wild-type mice after infection." (PMID 21629771, 2011). "We examined the airway responses of MDA5- and TLR3-deficient mice to infection with RV1B, a minor group virus which replicates in mouse lungs." (PMID 21637773, 2011). "We found that infection of mu-cDCs isolated from mice double deficient in MyD88 and TLR3 with the KOS strain of HSV-1 responded identically to mu-cDCs from wild-type control mice." (PMID 20174621, 2010). "Mice deficient in TLR3 were more resistant to rabies and had lower levels of infection in their brains." (PMID 19247444, 2009). "Overall, these data suggest that sustained TLR3 activation can be a critical component in the modulation of infection-associated inflammatory diseases." (PMID 19486528, 2009). "TLR3 deficient mice produced reduced pro-inflammatory mediators and are unable to control viral replication at the early stages of infection resulting in severe cardiac damage." (PMID 19122812, 2009). "Using mice deficient in TLR-3, it was determined that this receptor is dispensable in clearing VSV, as mice remained resistant to infection despite the loss of TLR-3 signaling." (PMID 21994572, 2009). "Adverse effects of TLR3 signaling were caused in part by an excessive inflammatory response to infection." (PMID 18802464, 2008). "TRIF−/− mice had less weight loss than wild-type mice on days 1–4 post-infection (p<0.05), which is similar to our published results for TLR3−/− versus wild-type mice." (PMID 18802464, 2008). "The different results observed in these studies may suggest that the effect of the TLR3 rs3775291 C/T polymorphism may depend on the type of virus causing the infection, since some viruses have different pathogenic components." (PMID 40831704, 2025). "TLR-3 plays an important role in the immune response to infections caused by viruses." (PMID 40531670, 2025). "Interestingly, TLR3 expression remained inducible upon infection, despite the loss-of-function mutation." (PMID 41453867, 2025). "Silva and colleagues published a meta-analysis study to determine whether there is an association between the rs3775291 SNP in TLR3 gene and susceptibility to infections." (PMID 40531670, 2025). "Loss of TLR3 partially alleviate the liver damage during infection." (PMID 38172683, 2024). "The purpose of the article was to determine whether there is an association between the Toll-like receptor 3 (TLR3) rs3775291 Single Nucleotide Polymorphism—SNP and susceptibility to infections." (PMID 37510216, 2023). "Another study on the role of TLR3 in SARS-CoV-2 infection, using SARS-CoV-2 to infect Calu-3/MRC-5 multicellular spheroids (MTCSs), found a prominent increase in TLR3-associated IRF3 expression during the first 24 h after infection, followed by IL-1α, Il-1β, IL-4, IL-6 and IFN-α and IFN-β." (PMID 36188605, 2022). "Additionally, TLR3-dependent immune responses are also implicated in other infections with neurotropic viruses." (PMID 34696494, 2021).
infection (continued). "Complete deficiency in TLR3 expression (TLR3-/-) inhibits survival after CB4 infection, whereas a slight loss in TLR3 expression (TLR3+/-) retains sufficient signaling function for protection against CB4 and another coxsackievirus associated with T1D, coxsackievirus B1 (CB1, not shown)." (PMID 34804036, 2021). "In our study, GNAstV infection caused increase of TLR3, RIG-1, and MDA-5 mRNA expression in the spleen and kidney, indicating that the innate immune system was activated which may contribute to inhibition of viral invasion." (PMID 33647718, 2021). "Notably, people with HSE and TLR3 pathway deficiency are usually resistant to other types of infections, including HSV-1-related diseases outside of the CNS." (PMID 34199501, 2021). "However, TLR3 rs3775296 SNP was significantly associated with such infection and appears to be a protective factor against HTLV-1 infection." (PMID 32578708, 2020). "We previously showed that TLR3-deficient mice exhibited significantly higher levels of chlamydial shedding from the lower genital tract when compared to wild-type (WT) mice during the first four weeks of infection." (PMID 30625140, 2019). "Also, we showed that there was a more rapid rate of decline in TER in the TLR3-deficient OE cells, which corresponded with a significantly increased rate in macromolecular permeability through the TLR3-deficient OE cell monolayers after 24hrs post-infection." (PMID 30625140, 2019). "The inoculation of LRV1-infected L. guyanensis promastigotes in the footpad of TLR3-deficient mice resulted in reduced swelling and lower parasite loads at the infection site compared to wild-type mice, confirming the involvement of this receptor in disease aggravation." (PMID 31847221, 2019). "Pretreatment of TLR3-deficient OE cells with 50U/ml exogenous IFN-β for 1hr before infection resulted in a significant reduction chlamydial progeny; however, pre-treatment with exogenous IFN-β had no significant impact on C. muridarum infection and replication in wild-type OE cells." (PMID 30625140, 2019). "Interestingly, these results are similar with previous findings that levels of TLR-7 and TLR-3 mRNA are barely up-regulated in response to highly pathogenic H7 infections, while rapid upregulation occurs following a lower pathogenic H7 infection." (PMID 30823888, 2019). "In corroboration with the western blot data, we saw substantially higher cellular expression levels of JAM-1 during C. muridarum infection in the TLR3-deficient OE cells, and its distribution along the outer membrane at cell-cell junctions increased at late times post-infection." (PMID 30625140, 2019). "The expression and cellular distribution of ZO-1 differed during TLR3-deficiency in that its protein expression levels dramatically decreased over the course of infection, and its distribution became increasingly cytoplasmic in the TLR3-deficient OE cells late during C. muridarum infection." (PMID 30625140, 2019). "Our results from time course analyses indicated that TLR3 degradation caused by EV-A71 infection could occur as early as 12 h post-infection, and the phenomenon became more evident after 24 h post-infection." (PMID 30563052, 2018). "On the other hand, the results of human genetic association studies suggest that the homozygocity for the low-expression rs3775291 allele of TLR3 is protective against neurotropic TBEV infection, consistent with the idea of TLR3 contributing to TBEV entry into CNS." (PMID 28646884, 2017). "Thus, we infected wild type mice (TLR3+/+) and mice deficient in TLR3 (TLR3−/−) with FV and analyzed the viral loads at days 4 and 10 post infection." (PMID 25539593, 2014). "TLR3-mediated immune-pathogenesis has also been observed for other viruses, such as influenza A virus and VV, evidenced by the findings that mice deficient in TLR3 produce less inflammatory cytokines and are more resistant to infections with influenza A virus or VV." (PMID 23435233, 2013).